RELN (reelin)
Diseases named in the same sentence as RELN in open-access papers (continued):
Sharing a sentence is not in itself a finding about the gene and the disease.
tumor (continued). "Unexpectedly, Reelin in tumor-infiltrating lymphocytes (ReelinTIL) was correlated with postoperative relapse." (PMID 34485127, 2021). "Comparison of primary tumor and metastasis cells from the same patient revealed up‐regulation of RELN and TBX2,TBX4 and TBX5 genes and down‐regulation of several HOXD genes." (PMID 29542868, 2018). "We looked for data sets in which Reelin expression was downregulated in tumours compared with healthy tissue with a P value below 0.05." (PMID 27071537, 2016). "Certain types of tumor also up-regulate reelin expression, including high Gleason score prostate cancer, esophageal carcinoma, and retinoblastoma." (PMID 26848618, 2016). "We observed that after disruption of the RAS-PI3-Kinase interaction, Reelin expression in tumours from Pik3caRBD/− mice was some fivefold higher than in Pik3caWT/− mice." (PMID 27071537, 2016). "Several studies matched these criteria (see list in ‘Methods' section), confirming that in several tumour types RELN expression is statistically significantly decreased when compared with their normal tissue counterparts." (PMID 27071537, 2016). "The other CRC-mucosa-secreted protein activating LRP8 receptor in tumor is Reelin (RELN), a glycoprotein that plays an important role in neuronal migration through the activation of lipoproteins receptors such as LRP8." (PMID 24597571, 2014). "Other interesting afferent crosstalk pairs involved LRP8 receptor in tumor activated by a double stimulus of RELN and CLU proteins secreted by adjacent mucosa, and VIP, an intestinal peptide that causes vasodilatation, linked to MME receptor in tumor cells." (PMID 24597571, 2014). "RELN may also indirectly affect tumor growth and spread by affecting astrocytes and microglia in the tumor microenvironment." (PMID 40171042, 2025). "Additionally, further studies are needed to explore the role of oligodendrocytes, neuron–tumor interactions such as neurotransmitter signaling and reelin resurgence, and cannabinoid receptors in controlling BM growth." (PMID 39858080, 2025). "Furthermore, the neuron-mediated reelin resurgence in tumor cells has been found to facilitate early CNS adaptation in vitro." (PMID 39858080, 2025). "Additionally, there was an increased expression of reelin, which aids in the integration of tumor cells within the brain parenchyma." (PMID 39858080, 2025). "Initially, we compared healthy tissue with increasing tumor grades, from I to IV, and could identify a continuous reduction in reelin expression correlating with the increasing tumor grade." (PMID 38543187, 2024). "Here, one could envision the utilization of TRUCKs (T cells redirected for universal cytokine-mediated killing) fourth-generation CAR (chimeric antigen receptor) T cells, to deliver a reelin peptide to the invading tumor cells and thus immobilize them." (PMID 38543187, 2024). "Additionally, we found that levels of both PLP1 and RELN were significantly associated with levels of CXCL12, which plays an important role in numerous physiological and pathological processes, including tumour metastasis." (PMID 38307969, 2024). "RAS/PI3‐kinase controlled RELN to promote cell motility and tumor metastases." (PMID 36703611, 2023). "Moreover, growing evidence implies this upregulation of Reelin is imperative for tumor metastatic progression." (PMID 34433809, 2021). "Furthermore, Reelin-related studies had focused on not only the tumor progression but also the immune function." (PMID 34485127, 2021). "After examined its regulatory roles in vitro, we explored whether Reelin can exert impacts on tumor development in vivo." (PMID 34433809, 2021). "Furthermore, consistent with its tumor attenuation function, Reelin knockdown alleviated MMBD by regulating OC and OB activity and rebalancing osteolysis and osteogenesis in MM model mice." (PMID 34433809, 2021). "The alterations in Reelin expression are related to the tumor metastasis and invasion." (PMID 34485127, 2021).
tumor (continued). "We furthermore evaluated the relationship between RELN and tumor immune microenvironment." (PMID 34485127, 2021). "Reelin has a great impact on carcinogenesis and tumor progression." (PMID 34485127, 2021). "In the present study, we found Reelin depletion reduced tumor progression in MM mice." (PMID 34433809, 2021). "Furthermore, the elevation of the taxa in family Halomonadaceae also correlated with the decreased expression of Reelin (RELN) in tumour tissues." (PMID 32321427, 2020). "Out of these, SFRP1, PI15 and RELN were downregulated as the tumor progresses toward malignancy." (PMID 30647841, 2018). "Several studies associated the presence or absence of reelin in tumor cells with the malignant proliferation of these cells." (PMID 28255385, 2017). "We detected RELN expression in both Pik3caWT/− and Pik3caRBD/− mice lungs, although expression in Pik3caRBD/− mice lungs was higher than in WT as observed in our MEFs and in tumours." (PMID 27071537, 2016). "We also report that Dab1 and Reelin are expressed in RB and NB cell lines suggesting that the Reelin-Dab1 signaling pathway may be active in these tumor cells." (PMID 22163036, 2011). "(iii) The Reelin pathway has been directly correlated with tumor aggressiveness." (PMID 20614023, 2010). "Therefore, we concluded that Reelin might have a versatile function in different cell types during the development of OSCC via governing tumor cell and stroma microenvironment." (PMID 34485127, 2021). "Gene enrichment analysis revealed that RELN and RPS6KA5 are associated with activation of cyclic AMP (cAMP) response element-binding protein (CREB) transcription factor (adjusted p-value<0.01), which is responsible for tumor initiation, progression, and metastasis." (PMID 32324757, 2020). "Thus, alteration of RELN may contribute to tumor cell invasion and spread in both the human and the dog." (PMID 26030765, 2015). "Notably, our findings reveal an unknown link between Snail, which triggers EMT process and favors tumor progression, and RELN gene." (PMID 22393371, 2012). "The expression of RELN, a regulator of neuronal migration, in normal brain slices and organoids, but not in co-cultures suggests that RELN expression may be modulated or downregulated in the tumor microenvironment, possibly after initial astrocyte recruitment has occurred." (PMID 40917877, 2025). "We pinpointed 8 human-derived genes (PHF14, PELP1, RPL7L1, HPRT1, RELN, RNU1-75P, RNU5A-8P, RNVU1-19), likely to represent tumor-specific signals as a signature combining these genes demonstrated high accuracy in assessing therapy response." (PMID 39337470, 2024). "Among these, ITGB8, RELN, and SPP1 were the top tumor-promoting candidates significantly downregulated (FDR < 0.05) by YBX1 knockdown in the ECM-receptor interaction pathway." (PMID 31481087, 2019). "Reelin thus plays a role in restraining RAS and PI3-kinase promotion of cell motility and potentially tumour metastasis." (PMID 27071537, 2016). "However, how reelin affects the adhesion, migration, and survival of tumor cells remains unclear." (PMID 26848618, 2016). "Perineural spread, associated with mutations in adhesion and axon guidance genes such as NTNG2 and RELN, enables tumor extension along nerve sheaths, often without overt mass formation." (PMID 41463022, 2025). "Importantly, these data sets do not allow speculation of the potential source of reelin, whether it is the particular brain region the tumor grows in, the non-tumorigenic cells that are associated with the tumor bulk, or, although counterintuitive, the tumor cells themselves." (PMID 38543187, 2024). "The expression of SCGN gene in HCC tumor tissues was significantly up-regulated (log2 fold change = 1.88, p < 0.01), while the expression level of RELN gene in HCC tumor tissues did not change significantly (log2 fold change = 0.84, p = 0.55)." (PMID 35034536, 2022).
tumor (continued). "The expression level of RELN gene in HCC tumor tissues did not change significantly, but it was down-regulated in sorafenib-resistant HCC cells." (PMID 35034536, 2022). "Taken together, our findings might suggest a potential involvement of the reelin signaling in GBM pathology and possibly in the onset of tumor recurrence that frequently originate from the peritumoral region." (PMID 34205192, 2021). "In the current study, we demonstrated that integrin α3β1, a major receptor for laminins in the ECM, represses the expression of the RELN gene in TNBC cells, thereby identifying a novel, integrin-dependent regulation of tumor cell secretome component that modulates invasive potential." (PMID 33477804, 2021). "In addition to SP1, tumor supporters such as E2F3a, BAX, BMI-1, DCX and Reelin are also targeted by miR-128." (PMID 24959930, 2014). "To investigate whether exogenous Reelin can induce Dab1 tyrosine phosphorylation in tumor cells, we treated RB522A cells with Reelin." (PMID 22163036, 2011). "However, clear evidence of the involvement of reelin in tumor development has not been fully elucidated." (PMID 34205192, 2021). "In addition, reelin may be involved in maintaining and stability of nerves architecture by VLDLR receptor coupling and in some circumstances, it facilitates normal or tumor melanocyte migration." (PMID 28255385, 2017).
neurodevelopmental disorder (22 papers, 2013 to 2025). A behavioral and cognitive disorder with onset during the developmental period that involves impaired or aberrant development of intellectual, motor, or social functions. "Mutations in the human gene RELN are linked to various neurodevelopmental disorders, including schizophrenia, bipolar disorder, and autism spectrum disorder." (PMID 35140590, 2021). "So far, limited studies study have investigated the contribution of reelin deficiency to the establishment of the early motor and social/communicative deficits present in these neurodevelopmental disorders." (PMID 23700474, 2013). "Reelin signaling also has been implicated in various neurodevelopmental disorders." (PMID 24409129, 2013). "It was shown that application of Reelin in older mice or in a model of a neurodevelopmental disorder improves synaptic function (↑ dendrite spine density and LTP) or restores behavioral and morphological deficits (mossy fibers; MF) in the hippocampus." (PMID 38283700, 2023). "In animal models and tissues from human patients, a defect in Reelin expression and/or secretion leads to severe neurodevelopmental disorders." (PMID 37288494, 2023). "Further study in preclinical models of neurodevelopmental disorders is required to clarify the effects of Reelin downstream from its lipoprotein receptors." (PMID 32982694, 2020). "This suggests that hypermethylation of the RELN promoter in both animal models and in patients with neurodevelopmental disorders epigenetically suppresses Reelin expression in the hippocampus, leading to cognitive and synaptic disturbances." (PMID 32982694, 2020). "Our results open the window for further studies on the interaction of reelin and serotonin and the pathogenesis of neurodevelopmental disorders." (PMID 30001399, 2018). "In the present study, we investigated the effect of Reelin microinjection into the mouse hippocampus on behavioral phenotypes to evaluate the role of Reelin in neurodevelopmental disorders and to test a therapeutic approach that extends beyond classical monoamine targets." (PMID 32982694, 2020). "Reelin injection into the brain to activate Reelin signaling pathways may thus be a novel therapeutic strategy for the treatment of neurodevelopmental disorders, though this remains untested." (PMID 32982694, 2020). "Inhibition of ADAMTS-3 may therefore reduce the amount of inactive Reelin and help to improve the symptoms seen in neurodevelopmental disorders." (PMID 32982694, 2020). "A significant contribution of reelin to the etiology of psychiatric and neurodevelopmental disorders has been proposed based on evidences of the pleiotropic roles of reelin in adult and developing brain together with patients’ data showing alteration in reelin levels." (PMID 28127276, 2016). "Animal models in which reelin expression is reduced or absent, provide important information about the role of reelin deficiency in the onset of neurodevelopmental disorders such as ASD." (PMID 25237666, 2014). "Nonetheless, our data provide support for the role of Reelin signalling in MIA-induced behavioural deficits, with particular relevance for neurodevelopmental disorders." (PMID 36979424, 2023). "There are many mutations in ECM genes, or genes affecting ECM function, that lead to neurodevelopmental disorders, with RELN (for the protein Reelin) being one the most well-known examples." (PMID 35140590, 2021).
neurological disorders (22 papers, 2007 to 2026). "This study revealed neuron-specific responses of Reelin, as well as a new function of Reelin in GABAergic inhibitory synapse development, which contributes to the cellular mechanisms underlying Reelin-associated neurological disorders." (PMID 34299127, 2021). "Research has shown that RELN is expressed in the adult brain and plays roles in neuronal plasticity, memory formation, and various neurological diseases." (PMID 40171042, 2025). "The expression of Reelin is dysregulated in these neurological disorders, showing common pathways depending on chronic neurogenic inflammation and/or dysregulation of the extracellular matrix in which Reelin plays outstanding roles." (PMID 40806482, 2025). "Disruption of the reelin or Lis1 gene leads to lissencephaly, a neurological disorder characterized by impaired neuronal migration in humans." (PMID 38137152, 2023). "Notably, dysfunction of cerebellar neurons likely contributes to many neurological disorders, including pathologies influenced by reelin." (PMID 41516385, 2026). "Reelin mRNA levels may reach a 50% reduction in some neurological disorders, accompanied by reduced expression of glutamic acid decarboxylase (GAD-67)." (PMID 34070424, 2021). "Thus, molecules involved in Reelin signaling could be potential targets for therapeutic intervention against neurological disorders." (PMID 28507985, 2017). "However, despite an obvious modulatory effect of Reelin proteolytic processing on its signaling activity and the described dysregulation of Reelin processing in several neurological disorders, the proteases (peptidases) responsible for Reelin processing remained unidentified." (PMID 23082219, 2012). "Based on these findings, we hypothesize that RELN and GSTO2 may act as protective factors against the development of these neurological disorders." (PMID 40171042, 2025).
neurodegenerative disease (19 papers, 2015 to 2025). A disorder of the central nervous system characterized by gradual and progressive loss of neural tissue and neurologic function. "Our work provides mechanistic insightsinto diverse neurodevelopmental and neurodegenerative diseases associatedwith Reelin signaling and suggests novel therapeutic strategies targetingHS sulfation." (PMID 41359976, 2025). "Recent studies have shown that the expression levels of Reelin protein are upregulated in the brain and CSF in several neurodegenerative diseases including AD, supporting the association of the Reelin protein with AD pathogenesis." (PMID 37626031, 2023). "As a result, there is a growing literature reporting that a loss of function and/or reduction of Reelin is implicated in numerous neurodegenerative diseases." (PMID 37891846, 2023). "Reelin-mediated reduction in signal transduction is associated with the pathogenesis of various neurodegenerative diseases, including AD and other age-related diseases." (PMID 34545285, 2021). "We have presented how there is a strong association of Reelin in many neurodegenerative diseases, which suggests that Reelin may offer a potential therapeutic target for disease intervention." (PMID 37891846, 2023). "Reelin pathways and protein cleavages are disrupted in neurodegenerative diseases, prospecting a potential role for this glycoprotein in the development of drugs specifically for counteracting the neuronal damage." (PMID 40867631, 2025). "Growing evidence suggests that Reelin signals and cleavages are affected in neurodegenerative diseases, prospecting a potential role for Reelin in the pathogenesis of neurodegenerative processes occurring in insulted retinas." (PMID 40867631, 2025). "Emerging evidence links Reelin to AD, a neurodegenerative disease characterized by the deposition of amyloid-beta (amyloid-β or Aβ) plaques and tau tangles in the brain." (PMID 40806482, 2025). "Reelin is increasingly recognized for its involvement in neurodegenerative diseases, particularly in AD." (PMID 40806482, 2025). "Despite these points, our findings support a possible link between retina and neurodegenerative diseases based on the relation between Reelin, Aβ1-42, FTH1 and TAU." (PMID 40867631, 2025). "First, we aimed to determine putative RELN changes in postmortem brain extracts by quantitative PCR in the different neurodegenerative diseases compared to nND samples." (PMID 32438605, 2020). "Reelin may prove to be a potential neurodegenerative disease biomarker through minimally invasive sample collection (blood or CSF) coupled with high-sensitivity immunoassays." (PMID 40806482, 2025). "Until now there has been little evidence for the use of Reelin detection as a prognostic and/or diagnostic biomarker for neurodegenerative disease." (PMID 40806482, 2025). "The study of specific isoforms of reelin in neurodegenerative diseases may be more specific diagnostically than the general measurement of reelin in CSF." (PMID 38137152, 2023). "Furthermore, very few data have been published describing putative Reelin changes in the CSF in other neurodegenerative diseases (i.e., α-synucleiopathies)." (PMID 32438605, 2020). "In addition, a compelling analysis of Reelin levels in neurodegenerative diseases other than AD is missing." (PMID 32438605, 2020). "Concerning the several neurodegenerative diseases analyzed in the present study, we found a progressive increase in RELN mRNA from nND or AD (III-IV) to AD(V-VI) stages in frontal cortex (area 8), which suggests increased RELN transcription in parallel with advanced neurodegenerative AD stages." (PMID 32438605, 2020). "Different Reelin fragments are altered in neuropsychiatric and degenerative diseases." (PMID 27065802, 2016). "Thus, brain levels of Reelin and, specifically, Reelin aggregates could be a possible biomarker of neurocognitive aging and need to be considered as a possible target in the treatment of neurodegenerative diseases." (PMID 37891846, 2023).
neurodegenerative disease (continued). "Also, activation of small GTPases or members of the CRK family as well as crosstalk with NMDA receptors can be implemented to shed light on the role of Reelin in neuronal positioning, dendrite outgrowth, modulation of synaptic plasticity and its role in neurodegenerative diseases." (PMID 29049379, 2017). "A correlative study of the brain levels and CSF levels of Reelin in different neurodegenerative diseases is lacking." (PMID 32438605, 2020).